SAMHD1 (SAM and HD domain containing deoxynucleoside triphosphate triphosphohydrolase 1)
Diseases named in the same sentence as SAMHD1 in open-access papers (continued):
Sharing a sentence is not in itself a finding about the gene and the disease.
infection (continued). "In the present study, we observed that the steady-state SAMHD1 protein level is reduced at late times of infection through a mechanism dependent on CRL complexes." (PMID 32850489, 2020). "SAMHD1 is the dominant host factor controlling post‐entry permissivity to infection of non‐dividing MDM." (PMID 32375558, 2020). "In similar virus-infected cells, we also measured SAMHD1 mRNA levels by qRT-PCR at 48 and 96 h after infection." (PMID 32850489, 2020). "Higher levels of SAMHD1 would restrict infection by degradation of the nucleotides pool for reverse transcription." (PMID 32656092, 2020). "Studies examining the role that SAMHD1 plays in infection of myeloid cells suggest that SAMHD1 restriction alone does not explain the extremely low levels of myeloid cell infection in vivo." (PMID 32992787, 2020). "Some lentiviruses have evolved countermeasures against SAMHD1; for example, the HIV-2 and SIVsm lineage encodes the Vpx protein, which degrades SAMHD1 and allows the infection of otherwise SAMHD1-positive target cells." (PMID 32751972, 2020). "After infection, a reproducible increase in SAMHD1 was seen in total cell lysates, with a similar trend in the two cell fractions." (PMID 32986788, 2020). "SAMHD1 also in vitro blocked infection by multiple other retroviruses such as HIV-2, FIV, bovine immunodeficiency virus (BIV), equine infectious anemia virus (EIAV), N-tropic murine leukemia virus (N-MLV), and B-tropic murine leukemia virus (B-MLV)." (PMID 31600877, 2019). "We noted comparable levels of virus internalization into Wt and Samhd1 KO cells during a short-term 6-h infection assay." (PMID 30918010, 2019). "Since our experiments focus on the first 3 d of infection and cccDNA is long-lived with an estimated half-life of 40 d in vitro, we are unable to assess the role of SAMHD1 in cccDNA maintenance." (PMID 30918010, 2019). "On the other hand, interactions of mDCs with T cells induce downregulation of SAMHD1 expression, allowing human primary mDCs to be more permissive to infection." (PMID 31244850, 2019). "These factors control or suppress HIVs ability to induce a productive infection with SAMHD1 as the major HIV suppressive factor." (PMID 31867020, 2019). "Degrading SAMHD1 by treating DCs with SIV-Vpx leads to infection and maturation of DCs promoting viral dissemination." (PMID 31354736, 2019). "Collectively, these results demonstrate that chimeric SIVs harboring a functional HIV-1 RT are nevertheless restricted by SAMHD1 and dependent on Vpx for infection of macrophages." (PMID 30656243, 2018). "That is, increased CD32 expression after infection of CD4+ resting T cells with a modified HIV-1 circumvents SAMHD1-induced restriction allowing productive infection." (PMID 30013105, 2018). "In some experiments, we compared infection of JRCSF packaged with Vpx (Vpx-JRCSF) with wild-type (WT) JRCSF to examine the role in mucosal infection of the HIV restriction factor SAMHD1, whose degradation is orchestrated by Vpx." (PMID 30532754, 2018). "Conversely, infection of cells depleted of SAMHD1 by treatment with Vpx containing particles (SIV3+) was both enhanced compared to untreated macrophages and was nearly completely resistant to inhibition by AhR activation." (PMID 30132758, 2018). "Concordantly, infection by HIV‐2 and SIVsm encoding the SAMHD1 antagonist Vpx was insensitive to ETO treatment." (PMID 29084722, 2018). "We show here that the ability of HIV-1 to infect MDMs results from the partial inactivation of SAMHD1 as a result of phosphorylation and that treatments that alter the phosphorylation state of SAMHD1 render the cells resistant to infection." (PMID 29515139, 2018). "Most reports agree that SAMHD1 restricts infection through its dNTPase activity, though there are some reports indicating that RNase activity is required for antiviral restriction." (PMID 30656243, 2018).
infection (continued). "SAMHD1-depleted macrophages were then infected with SIVwt or SIVΔvpx, and infection was monitored by the level of viral cDNA (2LTR circles) by qPCR." (PMID 30656243, 2018). "In other words, the RT-SHIV behaved much like wild-type SIV in that it was dependent on Vpx-mediated SAMHD1 elimination for infection of macrophages." (PMID 30656243, 2018). "During infection from S to G2/M phase (“inf 1”, 2–6 h post-release), SAMHD1 remains highly phosphorylated at T592 and cells are readily infected by HIV-1." (PMID 29884836, 2018). "To test this, we examined CDK1/2 expression knowing that CDK1/2 phosphorylates SAMHD1 to deactivate its capacity to restrict infection." (PMID 28122869, 2017). "Here, we propose that SAMHD1 is the dominant host factor controlling post‐entry permissivity to infection of non‐dividing MDM." (PMID 28122869, 2017). "As SAMHD1 is also highly expressed in activated CD4+ T-cells that support productive infection, several studies demonstrated posttranslational modification as a means of mechanistic regulation of SAMHD1 function in restricting HIV-1." (PMID 29176984, 2017). "Among the genes associated with responses to virus, TLR3, IRF1, GATA3, SAMHD1 and RSAD2 were all significantly up-regulated on both day 1 and day 3 post infection." (PMID 28486945, 2017). "Shortly after this SAMHD1 was found to be a deoxynucleoside triphosphate triphosphohydrolase (dNTPase) that restricts infection by lowering nucleotide concentrations below those which support viral DNA synthesis." (PMID 29056936, 2017). "SAMHD1 is expressed in monocytes where it acts as the major block to infection, as is clear from the ability of Vpx-containing viruses to efficiently infect these cells." (PMID 27905985, 2016). "DCs express SAMHD1, a phosphohydrolase that depletes the cell of deoxynucleotide triphosphates, thereby halting infection of HIV-1-based vectors at the level of reverse transcription." (PMID 27446074, 2016). "We report here, for the first time, that SAMHD1 restricts HBV in an infection model in hepatic cells." (PMID 27229711, 2016). "At two days post-treatment, SAMHD1 levels were significantly upregulated in all interferon and infection conditions, including an approximately eight-fold upregulation in response to interferon." (PMID 26936683, 2016). "Vpx-mediated degradation of SAMHD1 enables productive infection of human DCs and relieves a block to IFN induction and DC activation." (PMID 27477283, 2016). "In line with our conclusion that SAMHD1 limits immune responses, in vitro infection of DCs with HIV-2 results in potent IFN induction." (PMID 27477283, 2016). "Cell-autonomous virus restriction by SAMHD1, therefore, competes with sensors of infection and T cell responses." (PMID 27477283, 2016). "HIV-2 and some SIV isolates encode the accessory protein Vpx that counteracts this block to infection by binding to SAMHD1 and recruiting an E3 ubiquitin ligase complex, CRL4, to mediate its proteasomal degradation." (PMID 27446074, 2016). "Infection of BMMCs with both first- and second-generation lentiviruses was equally suppressed by SAMHD1." (PMID 27477283, 2016). "Overall, these data indicate that SAMHD1 restricts HBV replication in a bona fide infection model, thus indicating that SAMHD1 is a relevant restriction factor in the HBV life cycle." (PMID 27229711, 2016). "This increase in infection correlates with SAMHD1 protein down-regulation mediated by Vpx and has little to do with T cell activation." (PMID 26067822, 2015). "We found that, during infection by a panel of retroviruses, SAMHD1 specifically degraded retroviral genomic RNAs, thereby blocking productive infection." (PMID 26032178, 2015). "The SIV Vpx mutant is severely attenuated in establishing new infections in inoculated rhesus monkeys, in producing high levels of virus progeny, in degrading SAMHD1 in memory CD4+ T cell in infected animals, and in inducing symptomatic disease." (PMID 25996507, 2015).
infection (continued). "Susceptibility to infection is also heavily constrained by host cellular factors, from cell surface molecules, such as CCR5, to intracellular proteins, in which SAMHD1 is only the latest of a long list." (PMID 26407077, 2015). "Overall, this increase in infection suggests that knocking down SAMHD1 in resting CD4+ T cells biases the cells toward productive infection, an observation that is confirmed by calculating the ratio of latently infected to productively infected cells." (PMID 26067822, 2015). "This suggests that IL-7 treatment and SAMHD1 knockdown lead to silent infection events in resting CD4+ T cells, and, thus, an underestimation of the latently infected cell population." (PMID 26067822, 2015). "In retroviral infection assays we found that SAMHD1 blocks the infection of HIV reporter virus in vitro and in vivo." (PMID 26667483, 2015). "The extent of infection was measured by double staining for Gag and SAMHD1 after 3 days and analyzing by flow cytometry." (PMID 25582927, 2015). "The RNase activity of SAMHD1 led to an approximately 2-fold reduction in FIV cDNA synthesis at 24 h post-infection, demonstrating that RNase-mediated SAMHD1 function is required to prevent the production of viral cDNA intermediates." (PMID 26032178, 2015). "As expected, infection rates were boosted by SAMHD1 knock-down in MDDCs compared to scrambled control, most evident with Vesicular Stomatitis Virus envelope (VSV)-pseudotyped virus." (PMID 26208151, 2015). "The establishment of such a prodigious in vivo infection provided a window of opportunity to directly examine the status of endogenous SAMHD1 in memory CD4+ T cells during the acute infection." (PMID 25996507, 2015). "This suggests that replication kinetics of the virus follows an inverse relation with SAMHD1 and confirms that SAMHD1 is significantly regulated over the course of infection in astrocytes." (PMID 25890101, 2015). "Our results demonstrate that Vpx is critically important for countering SAMHD1 during SIVmac infections of memory CD4+ T lymphocytes both in vitro and in vivo." (PMID 25996507, 2015). "Subsequently, we analyzed SAMHD1 mRNA expression in the cells at these same time points following infection and compared with baseline." (PMID 25890101, 2015). "To further confirm our findings, that SAMHD1 phosphorylation is responsible for the efficient productive infection of DCs with HIV-C, we next pre-incubated DCs with the potent CDK2 inhibitor Roscovitine before exposure to virus." (PMID 26121641, 2015). "Only a single study has utilized replication-competent HIV-1 to monitor Vpx-mediated suppression of SAMHD1 during an in vitro infection." (PMID 25996507, 2015). "The observation that viruses bearing a polymerase with lower binding to nucleotides become increasingly sensitive to SAMHD1 strongly suggests that “dNTP starvation” is key to the mechanism by which SAMHD1 restricts infection." (PMID 24854580, 2014). "REAF is similar to already identified restriction factors TRIM5α, APOBECs and SAMHD1 because it acts at an early post-entry stage of infection." (PMID 24410916, 2014). "In agreement with this notion, SAMHD1 antagonism is actively maintained in natural infections, as exemplified by SIVagm vpr adaptations to SAMHD1 polymorphisms found in the African green monkey population." (PMID 24782834, 2014). "Vpx is a protein uniquely encoded by the HIV-2/SIVsmm and SIVrcm/SIVmnd-2 lineages, which has the property to favor myeloid cell infection through inducing the degradation of SAMHD1." (PMID 24782834, 2014). "Similar conclusions were drawn from infection experiments performed in the other strain of SAMHD1 knockout mice." (PMID 24854580, 2014). "Taken together, these results show that SAMHD1 not only controls infection in cultured cells but also in a living organism." (PMID 24854580, 2014). "SAMHD1 was reported to suppress infection of HIV-1-based lentivirus vectors containing VSV-G in cultured monocyte-derived macrophages." (PMID 24599229, 2014).
infection (continued). "Specifically, wild type and mutant SAMHD1 proteins were expressed to different levels in U937 cells by retroviral transduction at appropriate multiplicities of infection and then induced to differentiate by exposure to PMA." (PMID 23426366, 2013). "It is unlikely that SIV-WT or SIVsmmΔVpx preferentially infected untransfected HEK293T cells, because SIV-WT infection still resulted in transfected SAMHD1 degradation in these cells." (PMID 24035396, 2013). "Our data suggest that Vpx-mediated degradation of SAMHD1 to promote myeloid cell infection is usually preserved and thus advantageous in both viremic and aviremic HIV-2-infected individuals." (PMID 23497283, 2013). "Recent work identified SAMHD1 as the protein that blocks infection of SIV∆Vpx, HIV-2∆Vpx and HIV-1 before reverse transcription in macrophages, dendritic cells and resting CD4+ T cells." (PMID 24219908, 2013). "Our analyses showed that most vpx alleles from both seven highly viremic and four long-term aviremic HIV-2-infected individuals efficiently degrade SAMHD1 and promote macrophage infection." (PMID 23497283, 2013). "We found that efficient Vpx-mediated degradation of SAMHD1 to promote myeloid cell infection is usually preserved in both HIV-2-infected individuals that efficiently control the virus as well as in individuals that develop high viral loads and disease." (PMID 23497283, 2013). "Upon infection, virally co-packaged Vpx promotes proteasomal degradation of SAMHD1, leading to the rapid elevation of cellular dNTP concentrations and ultimately the acceleration of proviral DNA synthesis." (PMID 23825958, 2013). "The sterile alpha motif (SAM) and HD domain-containing protein-1 (SAMHD1) inhibits the infection of resting CD4+ T cells and myeloid cells by human and related simian immunodeficiency viruses (HIV and SIV)." (PMID 23874389, 2013). "Infections were carried out over a range of multiplicities of infection, to study SAMHD1 restriction over a broad range of SAMHD1 expression levels." (PMID 23426366, 2013). "For this purpose, we first identified the NLS of SAMHD1 and analyzed the ability of SAMHD1 NLS variants to block infection." (PMID 22691373, 2012). "Recent studies have now demonstrated that Vpx promotes macrophage and DC infection by targeting the cellular factor, SAMHD1." (PMID 23344558, 2012). "Based on these data, SAMHD1 is necessary and sufficient to inhibit infection of myeloid cells and quiescent CD4+ T cells by lentiviruses not expressing Vpx." (PMID 23344558, 2012). "Macrophages are generally susceptible to HIV-1, although they contain restriction factors, such as tetherin or SAMHD1, that can restrict the efficiency of infection but are actively counteracted by viral proteins." (PMID 23028330, 2012). "In the first approach, we transduced DCs with lentiviral particles coding for different shRNAs by co-infection with vpx-expressing lentiviruses to counteract the restriction factor SAMHD1 and facilitate DC productive infection." (PMID 23271952, 2012). "Recent work identified SAMHD1 as the protein that blocks infection of SIVΔVpx and HIV-1 before reverse transcription in macrophages and dendritic cells." (PMID 22691373, 2012). "Instead, this type-I IFN-derived restriction became active only if infection was successful beyond SAMHD1’s restricting ability." (PMID 21994799, 2011). "Recently, it was reported that Vpx from HIV-2/SIVsm facilitates infection of these cells by counteracting the host restriction factor SAMHD1." (PMID 22174685, 2011). "Because Vpx induces degradation of SAMHD1, depletion via RNAi should phenocopy the expression of Vpx, and consequently render cells more permissive to infection." (PMID 21994799, 2011). "Laguette and colleagues showed that siRNAs directed against SAMHD1 indeed were able to render dendritic cells between 6- and 34-fold more sensitive to infection by various HIV-1-derived lentiviral vectors." (PMID 21994799, 2011).
infection (continued). "The first level of restriction limits infection at an early step of the viral life cycle (reverse transcription) and is effected by SAMHD1." (PMID 21994799, 2011). "Vpx VLPs enhance infection rates in myeloid cells by targeting SAMHD1 for degradation." (PMID 41118075, 2025). "Considering the differences in the kinetics of HIV-1 reverse transcription in cells treated with HU or COH29 became evident as early as 3 h post-synchronized infection, we became curious about the dynamics of SAMHD1 expression when the de novo pathway is blocked." (PMID 40586616, 2025). "Then, we further investigated whether HIV-1NL4-3 infection affected the interaction between SAMHD1 and BIK in THP-1 Ctrl cells using Co-IP." (PMID 40434097, 2025). "This supports their conclusion that SAMHD1 expression in CD11c+ ASDCs limits productive infection." (PMID 39861894, 2025). "The protein level of SAMHD1 increased slightly at 24 and 12 h after infection and then decreased." (PMID 38287375, 2024). "The identification of SAMHD1 as a major target for HIV-2 Vpx-mediated degradation helped to explain the previously elusive mechanism by which Vpx markedly enhanced myeloid lineage cell infection." (PMID 39205287, 2024). "DNA viruses antagonize SAMHD1 to ensure successful infection." (PMID 39339888, 2024). "However, although SAMHD1 in 293T cells was upregulated and then decreased after infection, the change was less significant than that in A549 cells." (PMID 38287375, 2024). "To investigate this, we employed a “Vpx rescue” assay to measure how long after infection the introduction of Vpx could relieve restriction by SAMHD1 and rescue HIV-1 replication." (PMID 37127613, 2023). "In addition, the increased expression of UNG and SAMHD1 in AM post-infection is too slow to prevent integration." (PMID 36114511, 2022). "Our research suggests that therapeutic targeting of S1P availability early in infection via SPHK inhibition and phosphorylated SAMHD1 modulation will aid in the development of strategies to prevent establishment of initial infection and hinder cell-to-cell transmission of HIV-1 in CD4 T cells." (PMID 35412343, 2022). "Indeed, to achieve infection of monocyte-derived macrophages in vitro with HIV-1, which does not encode Vpx, research teams will often deliver SIV Vpx exogenously to degrade SAMHD1 before challenge." (PMID 36015010, 2022). "One intriguing idea is that the advantage to infect macrophages more efficiently by degrading SAMHD1 may be opposed in vivo by a simultaneously enhanced infection of DCs, resulting in a stronger antiviral immune response." (PMID 33801276, 2021). "SAMHD1 was also found to potently inhibit the infection of vaccinia virus (VACV), a member of the poxvirus family, and the α-herpesvirus herpes simplex virus 1 (HSV-1) by limiting intracellular dNTP levels through its dNTP hydrolase activity in nondividing myeloid cell lines." (PMID 33801276, 2021). "This highlights that targeting the phosphorylation of SAMHD1 may be an effective way to control various infections." (PMID 34835003, 2021). "Loss of SAMHD1 can trigger the activation of antiviral signaling pathways, suggesting Vpx may have both SAMHD1-dependent and independent functions with regard to stimulation of innate immune responses during infection." (PMID 33563288, 2021). "In addition, genes encoding, for example, APOBEC3 (apolipoprotein B mRNA editing enzyme catalytic polypeptide 3) family members, SLFN11, and SAMHD1 were enriched in CD3ko-Nef versus WT SIVmac239 infection." (PMID 32075764, 2020). "An upregulation of SAMHD1 by LPS induced acute lung injury in as early as 6 h of post-stimulation and was thought to be one of the early cellular responses and an effector of innate immunity after infection." (PMID 32670284, 2020).